E2F3 (E2F transcription factor 3)
Diseases named in the same sentence as E2F3 in open-access papers (continued):
Sharing a sentence is not in itself a finding about the gene and the disease.
congestive heart failure (3 papers, 2017 to 2023). Failure of the heart to pump a sufficient amount of blood to meet the needs of the body tissues, resulting in tissue congestion and edema. "Among this factors, E2F3 knockout mice have dysplasia or congestive heart failure, indicating that E2F3 plays an important role in the development of the cardiovascular system or maintenance of its normal functions." (PMID 37980402, 2023). "E2F3 knockout mice have dysplasia or congestive heart failure, suggesting that E2F3 plays an important role in the development of the cardiovascular system or in maintaining normal functions." (PMID 32420356, 2020). "E2F3 knockout mice have dysplasia or congestive heart failure, indicating that E2F3 plays an important role in the development of the cardiovascular system or maintenance of its normal functions." (PMID 32420356, 2020). "The great majority of E2f3 knock-out mice die between E13.5 and P2 dpc20, exhibiting fatal cardiac abnormalities and typical signs of congestive heart failure." (PMID 28855541, 2017).
lung squamous cell carcinoma (3 papers, 2018 to 2025). "Sun and colleagues have indicated that the levels of E2F1 and E2F3 expression were increased in LUAD and lung squamous cell carcinoma (LUSC) tissues." (PMID 40070576, 2025).
renal carcinoma (3 papers, 2017). A carcinoma arising from the epithelium of the renal parenchyma or the renal pelvis. "Out of the unique set of genes detected by BNNPT, a few were reported to be relevant to renal cancer or disease: CDCP1, GSTT1, E2F3, MAPK1, SALL4, SIRT1, ADAMTS13, Gfrα1, ASPH, MIR17HG, APOE, BMP4, RCOR1, NUMB and SEC63." (PMID 28986523, 2017). "Real-time and Western blot tests were applied in human renal cancer cell lines ranged from low in ACHN cells to high in OS-RC-2 and 786-O cells, depending on endogenous E2F3 protein levels." (PMID 28903320, 2017). "Of the deregulated target genes expressed significantly in the current renal cancer specimens, MET and E2F3 were significantly upregulated in RCC compared to noncancer tissues with high diagnostic performance." (PMID 29104726, 2017).
renal cell carcinoma (3 papers, 2017). "In renal cell carcinoma, miR-429 was found to function as a tumor suppressor via regulation of E2F3, suggesting this potential development of miR-429-based prognostic and therapeutic approaches may be valuable for the treatment of renal cell carcinoma patients." (PMID 28947999, 2017). "Meanwhile, miR-429 was reported to exert its tumor suppressive effect in renal cell carcinoma by directly targeting BMI1 and E2F3." (PMID 28947999, 2017).
Age-related cataract (2 papers, 2019 to 2021). A type of cataract (opacification of the lens) that forms during the course of aging. "Dysregulation of E2F3 expression is linked to diverse diseases, such as age-related cataracts and Hirschsprung’s disease." (PMID 34644734, 2021). "A novel mechanism of microRNA-15a/BCL2/E2F3 axis in age-related cataracts was revealed in our present study." (PMID 31737898, 2019). "In summary, the results of our present study demonstrated that microRNA-15a was able to modulate lens epithelial cells apoptosis and proliferation through targeting BCL2 and E2F3 in age-related cataracts." (PMID 31737898, 2019).
angiosarcoma (2 papers, 2022 to 2024). A malignant tumor arising from the endothelial cells of the blood vessels. "For example, miR-210 has been shown to promote angiosarcoma cell proliferation by targeting ephrin A3 and E2F3, proteins involved in cell growth and division." (PMID 38826780, 2024).
asthma (2 papers, 2019 to 2022). "TUG1, serving as the molecular sponge of miR-138-5p, miR-590-5p, miR-216a-3p, and miR-181b, has been confirmed to be involved in ASMC proliferation and migration in human asthma by modulating E2F transcription factor 3 (E2F3), fibroblast growth factor 1 (FGF1), Smurf2 and HMGB1, respectively." (PMID 35769905, 2022). "Through mediating E2F transcription factor 3 (E2F3) expression, lncRNA plasmacytoma variant translocation 1 (PVT1) is deemed to be correlated with the effects of α-asarone in the treatment of RSV-induced asthma." (PMID 31223533, 2019).
cholangiocarcinoma (2 papers, 2022 to 2024). A carcinoma that arises from the intrahepatic biliary tree (intrahepatic cholangiocarcinoma) or from the junction, or adjacent to the junction, of the right and left hepatic ducts (hilar cholangiocarcinoma). "TAM-derived exosomes delivered Circ_0020256, which targets miR-432-5p and E2F3 to increase the activity of cholangiocarcinoma cells and promote cholangiocarcinoma development." (PMID 38731840, 2024). "Exosomes secreted by TAM contained highly expressed hsa_circ_0020256, which enters cholangiocarcinoma (CCA) cells and causes upregulation of hsa_circ_0020256, and further upregulates E2F3 by sponging miR-432-5p, thus enhancing the proliferation, invasion and metastasis of CCA cells." (PMID 36238299, 2022).
endometriosis (2 papers, 2021 to 2022). The growth of functional endometrial tissue in anatomic sites outside the uterine body. "Moreover, miR-20a targets E2F transcription factor 3 (E2F3) and Cyclin D1 (CCND1), and thus participates in epithelial cell proliferation and decreased apoptosis (antiapoptotic action); it also targets interleukin-8 (IL-8) and TGF-β, which promotes epithelial–mesenchymal transition in endometriosis." (PMID 34449536, 2021).
esophageal squamous cell carcinoma (2 papers, 2020 to 2022). Esophageal squamous cell carcinoma (ESCC) is a type of esophageal carcinoma (EC) that can affect any part of the esophagus, but is usually located in the upper or middle third. "Correlations of circ_0087378, miR-140-3p, and E2F3 expression with clinicopathologic features of esophageal squamous cell carcinoma." (PMID 33680929, 2020). "It has been reported that E2F3, one transcription factor (TF) of E2F family proteins, regulated expression of RACGAP1 in in esophageal squamous cell carcinoma." (PMID 35958019, 2022).
gastric adenocarcinoma (2 papers, 2019 to 2021). "The data showed that E2F3 expression in the normal gastric epithelial cell line GES-1 was notably less than that in the human gastric adenocarcinoma cell lines." (PMID 31423109, 2019).
intervertebral disc degeneration (2 papers, 2023 to 2025). "Recently, the increased m6A modification level of NORAD reduced the sealing effect of PUMILIO protein, inhibited the expression of E2F3, and led to the aging of nucleus pulposus cells and intervertebral disc degeneration." (PMID 37517088, 2023).
ischemic heart disease (2 papers, 2013 to 2020). "For example, enhanced expression of E2F3 was reported to facilitate endothelial cell growth and further accelerate ischemic cardiac repair in ischemic heart disease." (PMID 32348429, 2020). "Thus, E2F3 promotes while E2F2 suppresses ischemic cardiac repair through corresponding changes in EC proliferation; and differential targeting of specific E2F members may provide a novel strategy for therapeutic angiogenesis of ischemic heart disease." (PMID 23799044, 2013).
myocardial infarction (2 papers, 2013 to 2025). Gross necrosis of the myocardium, as a result of interruption of the blood supply to the area, as in coronary thrombosis. "Furthermore, miR-147a directly interacts with myocardial infarction-associated transcript (MIAT), and E2F transcription factor 3 (E2F3) has been established as the target gene of miR-147a." (PMID 40282196, 2025). "In this study, we sought to investigate the roles of E2F2 and E2F3 in EC proliferation and their functional impact on myocardial infarction (MI)." (PMID 23799044, 2013). "Here we investigated the roles of E2F2 and E2F3 in EC growth, angiogenesis, and their functional impact on myocardial infarction (MI)." (PMID 23799044, 2013).
Obesity (2 papers, 2023). Accumulation of substantial excess body fat. "E2F3 and PGC-1α levels are coordinately reduced in states of obesity — HFD-fed mice, Lepob/ob mice, and overweight and obese humans — consistent with a conserved underlying mechanism." (PMID 37395281, 2023).
ovarian serous carcinoma (2 papers, 2012 to 2019). "In the TCGA dataset, the fold change of mRNA expression of E2F3 in ovarian serous carcinoma was 2.013 and p–value of 1.96E-11." (PMID 30967995, 2019). "In Welsh's dataset, E2F3 was upregulated in ovarian serous carcinoma with a fold change of 2.574 and p–value of 3.40E-07." (PMID 30967995, 2019). "The E2F transcription factor 3 (E2F3), a gene that is up-regulated in serous ovarian carcinomas, regulates crucial cell cycle and tumour suppressor genes." (PMID 22452920, 2012).
retinal degeneration (2 papers, 2014 to 2018). Degeneration of the retina. "MiRNA deregulation is likely not involved in the retinal degeneration phenotype characteristic of Rb loss as both E2f1 TKO and E2f3 TKO retinae show similar patterns of miRNA expression." (PMID 25338120, 2014).
viral infection (2 papers, 2016 to 2024). "Moreover, E2F3 is usually downregulated by miRNAs to avoid cell proliferation, which is usually very related to viral infections." (PMID 38778280, 2024). "Among the differential ASEs associated with viral infection, at least 10 ASEs resulted in the addition or loss of predicted nuclear localization signals (NLS) including the CDC-Like Kinase 4 (CLK4), the e2F3 transcription factor, and the Influenza Virus NS1A Binding Protein (IVNS1ABP)." (PMID 27598998, 2016).
adenoma (1 paper, 2025). A neoplasm arising from the epithelium. "The paired analysis further reinforced this finding with 73% of the 66 paired samples exhibited higher levels of E2F3 in adenomas (p = 0.0001)." (PMID 40699620, 2025). "For E2F3, mean expression was significantly higher in adenomas (1.81) than in adenocarcinomas (1.49) (p = 0.0007)." (PMID 40699620, 2025).
anaplastic large cell lymphoma (1 paper, 2022). Anaplastic large cell lymphoma (ALCL) is a rare and aggressive peripheral T-cell non-Hodgkin lymphoma, belonging to the group of CD30-positive lymphoproliferative disorders, which affects lymph nodes and extranodal sites. "In addition, Hoareau-Aveilla C. and colleagues studied its role in NPM-Anaplastic large cell lymphoma (NPM -ALK+ ALCL) cells, where it regulates the expression of cyclin E1, CDK6, and E2F3." (PMID 36498861, 2022).
bile duct cancer (1 paper, 2022). "Multiple reports have shown that FOXD2-AS1 plays an important role in the development of multiple tumors, including the promotion of malignant progression of bile duct cancer via regulation of the miR-760/E2F3 axis." (PMID 36072656, 2022).
brain trauma (1 paper, 2018). "E2F2 and E2F3 were sensitized to neuronal cell loss after brain trauma." (PMID 30627556, 2018).
breast adenocarcinoma (1 paper, 2022). "Overexpress of E2F1 and E2F3 were found in breast adenocarcinoma when compared to normal breast tissues." (PMID 36424626, 2022).
cataract (1 paper, 2020). Partial or complete opacity of the crystalline lens of one or both eyes that decreases visual acuity and eventually results in blindness. "We hypothesized that miR-378a-5p and miR-630 could interact with the target gene E2F3 and further regulate cell behavior in cataract." (PMID 32348429, 2020).
Cirrhosis (1 paper, 2012). A chronic disorder of the liver in which liver tissue becomes scarred and is partially replaced by regenerative nodules and fibrotic tissue resulting in loss of liver function. "Overall, critical genes encoding for positive cell cycle progression factors (CCND1, CDK1, CDK2, E2F3, EIF4E, and MDM2) were found significantly up-regulated in HCV-cirrhosis with HCC." (PMID 22792259, 2012).
colorectal adenocarcinoma (1 paper, 2021). The most common type of colorectal carcinoma. "The cBioPortal database was used to analyze the mutations of seven genes, which showed that E2F3, ETS2, HLF, HSF4, KLF4, MEIS2, and TCF7L1 were altered in 8, 8, 6, 6, 5, 9, and 6% of 524 colorectal adenocarcinoma patients separately." (PMID 34603375, 2021).
diabetic angiopathy (1 paper, 2020). "In order to further study the pathogenesis of diabetic angiopathy, we have demonstrated through this experiment that the E2F3 transcription factor plays an important role in regulating vascular endothelial cell function." (PMID 32420356, 2020). "Our study found for the first time that E2F3 was inhibited in high-glucose states, suggesting that the E2F3 transcription factor pathway may play an important role in diabetic angiopathy." (PMID 32420356, 2020). "In summary, in order to further study the pathogenesis of diabetic angiopathy, we propose the following hypotheses: E2F3 transcription factor plays an important role in regulating vascular endothelial cell function." (PMID 32420356, 2020).
dysplasia (1 paper, 2017). A usually neoplastic transformation of the cell, associated with altered architectural tissue patterns. "We identified E2F3 and DMBT1 as the genes with the largest change in expression when dysplasia samples were compared to MAG (29% reduction for E2F3 and 2.5 -fold increase for DMBT1)." (PMID 28423364, 2017).
ependymoma (1 paper, 2021). A WHO grade II, slow growing tumor of children and young adults, usually located intraventricularly. "Among them inverse correlations (r > −0.61) were noted in the ependymoma group for miR-106b-MYCC, miR-106b-MYCN, miR-106b-E2F2, miR-106b-E2F3, miR-93-MYCN, miR-25-MYCN, miR-25-E2F2, miR-25-E2F3, i.e., members of the miR-106b-25 cluster." (PMID 33430425, 2021). "In ependymomas, gene expression negatively correlated with the expression of cluster members, e.g., miR-106b-MYCC r = −0.42, miR-106b-MYCN r = −0.61, miR-106b-E2F2 r = −0.51, miR-106b-E2F3 r = −0.58, miR-93-MYCN r = −0.47, miR-25-MYCN r = −0.47, miR-25-E2F2 r = −0.49, miR-25-E2F3 r = −0.52." (PMID 33430425, 2021).
focal segmental glomerulosclerosis (1 paper, 2024). A renal disorder characterized by sclerotic lesions in the glomeruli. "Studies show that del(6p) is associated with the development of focal segmental glomerulosclerosis causing dysregulation of VEGF (vascular endothelial growth factor) synthesis caused by the deletion of the E2F3 gene." (PMID 39767649, 2024).
gastric tumor (1 paper, 2025). "Prior studies have indicated that E2F3 overexpression promotes gastric tumor cell growth and correlates with poor patient outcomes." (PMID 41291892, 2025). "Similarly, previous transcriptomic analyses have documented increased THBS2 and E2F3 expression in advanced gastric tumors, which aligns with the significant overexpression detected across our datasets and validated in STAD cell lines." (PMID 41291892, 2025).
gynecological cancers (1 paper, 2025).
HCMV infection (1 paper, 2011). "E2F1, but not E2F2 or E2F3, promotes the accumulation of γH2AX during HCMV infection or IE protein expression." (PMID 21589897, 2011).
Hepatic steatosis (1 paper, 2015). Steatosis is a term used to denote lipid accumulation within hepatocytes. "While no studies have examined the relationship between E2F3 and hepatic steatosis, E2F3 was found to be increased in the liver of HF-induced hepatic steatosis of mice (GDS4013) and clinical alcohol-induced hepatitis (GDS4389) in GEO." (PMID 26052340, 2015).
inflammatory bowel disease (1 paper, 2025). A spectrum of small and large bowel inflammatory diseases of unknown etiology. "Two disease-related pathways — inflammatory bowel disease (cfa05321; GATA3, TLR4) and cancer pathways (cfa05222; COL4A1, E2F3, RARB) — were also enriched." (PMID 40764990, 2025).
intestinal cancer (1 paper, 2018). "E2F3 mRNA expression was significantly associated with poor OS for all GC patients and intestinal cancer patients, HR = 1.88 (1.57–2.26), P=4.2 × 10−12, HR = 2.34 (1.7–3.21), P=7.4 × 10−8 respectively." (PMID 30487158, 2018).
kidney cancer (1 paper, 2017). Primary or metastatic malignant neoplasm involving the kidney. "BNNPT is still capable of distinguishing between kidney cancer and normal groups under complex distributions, such as the bimodal distribution in E2F3, to identify the target gene." (PMID 28986523, 2017).
lactic acidosis (1 paper, 2010). Metabolic acidosis characterized by the accumulation of lactate in the body. "Among clusters of genes repressed by lactic acidosis in the later time points is a large group whose expression is closely linked to cell proliferation (cyclin D, PCNA, CCRK, E2F3, and E2F6)." (PMID 20844768, 2010).
large-cell lung carcinoma (1 paper, 2018). "E2F3 overexpression is also found in large-cell lung carcinoma with a fold change of 2.338 in Hou’s dataset and in SCLC with a fold change of 2.006 in Talbot’s dataset." (PMID 29754146, 2018).
laryngeal carcinoma (1 paper, 2013). Carcinoma that arises from the laryngeal epithelium. "The Src, β-catenin and E2F3 pathways did not appear to be associated with DFS in patients with laryngeal cancer." (PMID 23950933, 2013).
leukemia (1 paper, 2023). A malignant (clonal) hematologic disorder, involving hematopoietic stem cells and characterized by the presence of primitive or atypical myeloid or lymphoid cells in the bone marrow and the blood. "employed the SCENIC network to delineate a subset of cells characterized by activation of CDK6 and E2F3, subsequently categorizing them as leukemia cells associated with cell cycle initiation." (PMID 38022588, 2023).
leukopenia (1 paper, 2017). "Repressing E2f3 in E2f1−/−; E2f2−/− doubly-deficient mice triggered profound collapse of bone marrow, together with the onset of leukopenia, thrombocytopenia and progressive erythrocytopenia, with corresponding decreases in lymphocyte and myeloid cell populations." (PMID 28855541, 2017).
liver fibrosis (1 paper, 2021). "Moreover, conditional knockout E2F3 reduced liver fibrosis and HSCs activation." (PMID 34873170, 2021). "Cre-loxP-mediated E2F3 gene deletion in activated-HSC-MFs inhibited HCC growth in mice and CCl4-induced HSC activation and liver fibrosis." (PMID 34873170, 2021). "In addition, we used CCl4 to induce liver fibrosis and found that E2F3 was increased in CCl4-induced liver, moreover, CCl4-mediated HSC activation was reduced in E2F3 F/F cre livers (P < 0.05 by t-test)." (PMID 34873170, 2021).
liver tumor (1 paper, 2015). "The expression levels of Akt3 and E2F3 in those liver tumor tissues with miR-424 overexpressed were down-regulated compared with control group." (PMID 26315541, 2015).
lymphoma (1 paper, 2009). A malignant (clonal) proliferation of B- lymphocytes or T- lymphocytes which involves the lymph nodes, bone marrow and/or extranodal sites. "In contrast to the results seen with the E2f1 and E2f3 knockout animals, a deficiency of E2F2 dramatically accelerated the appearance of lymphoma." (PMID 19749980, 2009). "Lymphoma onset was also not appreciably influenced by E2F3 status." (PMID 19749980, 2009).
meningioma (1 paper, 2012). A generally slow growing tumor attached to the dura mater. "In our study, fibroblastic meningioma was detected with increasing expression of CCND1, CDK6, and E2F3, and decreasing expression of CDKs inhibitors including CDKN1A, CDKN2A, and CDKN2B, suggesting a role of cell cycle deregulation in the tumorigenesis of fibroblastic meningioma." (PMID 23285163, 2012).
metabolism (1 paper, 2019). "Some studies predicted that E2F3 transcription factor might be a promising biomarker in various cancer and metabolism diseases." (PMID 31419939, 2019).